ATP1A2 (ATPase Na+/K+ transporting subunit alpha 2)
Diseases named in the same sentence as ATP1A2 in open-access papers (continued):
Sharing a sentence is not in itself a finding about the gene and the disease.
epilepsy (28 papers, 2011 to 2025). A brain disorder characterized by episodes of abnormally increased neuronal discharge resulting in transient episodes of sensory or motor neurological dysfunction, or psychic dysfunction. "ATP1A2 mutations cause variable phenotypes such as hemiplegia, epilepsy, and intellectual disability." (PMID 37408271, 2023). "A recent review demonstrated that among the three monogene mutations causing FHM, most cases associated with epilepsy occurred in ATP1A2 mutations." (PMID 34384358, 2021). "ATP1A2 mutations cause phenotypes ranging from pure FHM to FHM with epilepsy and intellectual disability due to varying degrees of deficits in biochemical and electrophysiological properties of Na+/K+-ATPase." (PMID 34384358, 2021). "The clinical presentation of FHM2 with mutations in the same gene varies from pure FHM to severe variant forms with epilepsy and intellectual disability, but the correlation of these symptoms with different ATP1A2 mutations is still unclear." (PMID 34384358, 2021). "In conclusion, this study provides a comprehensive delineation of the phenotypic spectrum with ATP1A2 mutations ranging from pure FHM to FHM with epilepsy and/or intellectual disability." (PMID 34384358, 2021). "There is increasing evidence that ATP1A2 mutations are also related to epilepsy, emotional disorders, and AHC, although the number of cases of AHC caused by ATP1A2 is small compared to that caused by ATP1A3." (PMID 33544780, 2021). "The clinical presentation of FHM2 with mutations in the same gene varies from pure FHM to severe forms with epilepsy and intellectual disability, but the correlation of these symptoms with different ATP1A2 mutations is still unclear." (PMID 34384358, 2021). "ATP1A2 has been associated, in several studies, to rare forms of epilepsy and seizures." (PMID 33557955, 2021). "Additionally, ATP1A2 has been identified as a potential gene associated with human epilepsy." (PMID 38676299, 2024). "The seizure management with levetiracetam also reflects established practice for ATP1A2-related epilepsy." (PMID 41146775, 2025). "Its target gene, the alpha 2 subunit of Na+, K+‐ATPase (ATP1A2), has a close connection to epilepsy." (PMID 38676299, 2024). "In this regard, the authors find that interactions of circEFCAB2 with miR-485-5p and circ-DROSHA with miR-1252-5p were highly correlated with the expression of epilepsy-associated genes CLCN6 and ATP1A2, respectively." (PMID 35328484, 2022). "ATP1A2 mutations with distinct phenotypes were grouped as pure FHM (FHM), FHM with epilepsy (FHME), and FHM with epilepsy and intellectual disability (FHMEI)." (PMID 34384358, 2021). "A missense variant in the human ATP1A2 gene causes Hemiplegia, including numerous motor abnormalities, although variations in this gene are not linked to epilepsy." (PMID 22675444, 2012). "ATP1A2 missense mutations were marked by the associated clinical symptoms: pure HM, HM with epilepsy, HM with ataxia, and HM with intellectual disability (with or without epilepsy)." (PMID 34384358, 2021). "Further analysis conducted on ATP1A2, SLC2A1, SLC2A2 KCNMA1 and KCNN3 showed they all are related to epilepsy or seizures." (PMID 27984588, 2016). "It has been established that in addition to FHM2, mutations in ATP1A2 can also lead to AHC accompanied by mental retardation with or without epilepsy, suggesting a clinical overlap with FHM." (PMID 34384358, 2021).
Ataxia (7 papers, 2016 to 2025). Ataxia refers to impaired coordination of voluntary muscle movement. "Individuals with ATP1A2/ Na/K ATPase α2 mutations often exhibit cognitive impairments, ataxia, sensory disturbances, and seizures." (PMID 39103699, 2024). "In Belgian Shepherds, a SINE insertion in exon 2 of the ATP1A2 gene probably causes spongy degeneration with cerebellar ataxia (SDCA2) by complete skipping of exon 2 or activation of cryptic splice sites." (PMID 33494213, 2021).
alternating hemiplegia of childhood (6 papers, 2016 to 2023). A rare neurodevelopmental disorder characterized by recurrent episodes of hemiplegia and paroxysmal disturbances associated with persistent developmental delay and cognitive impairment. "ATP1A2 gene mutation has been indicated to cause alternating hemiplegia of childhood (AHC); however, limited evidence supports this relationship so far." (PMID 33794876, 2021). "While some ATP1A2 mutations can cause alternating hemiplegia of childhood (AHC), the majority of cases are caused by mutations in ATP1A3." (PMID 33126486, 2020).
Anxiety (6 papers, 2006 to 2025). Intense feelings of nervousness, tension, or panic often arise in response to interpersonal stresses. "Studies in Atp1a2-deficient mice suggest an association of the protein with anxiety, learning disorders, and fear." (PMID 23561701, 2013). "A general behavior characterization by a modified SHIRPA protocol shows a higher susceptibility to fear and anxiety in Atp1a2+/R887 mice." (PMID 21731499, 2011). "Moreover, it confirms that genetic alteration in Atp1a2, the encoding gene of Na+/K + ATPase α2 isoform, affects locomotor activity and cause anxiety and depressive-like behavior." (PMID 41146349, 2025). "Additionally, heterozygous Atp1a2 deficient mice showed augmented fear and anxiety behaviours and enhanced neuronal activity in the amygdala and piriform cortex after conditioned fear stimuli." (PMID 16772024, 2006). "Additional upregulated genes included Enpp2, Atp1a2, Apoe and Slc1a3, which play a role in psychiatric conditions often related to withdrawal, such as anxiety and depression." (PMID 36534642, 2022). "Genetic studies in mice have revealed other neurological effects of Atp1a2 in mice including anxiety, fear, and learning and motor function disorders." (PMID 23561701, 2013). "They examined the role of Atp1a2 in neural activity by measuring fear and anxiety in heterozygous mice." (PMID 23561701, 2013). "No major differences in the sensory-motor functions were observed between heterozygous Atp1a2+/R887 (n = 8) and wild-type (n = 6) mice, except for a higher fear and anxiety of Atp1a2+/R887 at the specific tests of transfer arousal and fear (p<0.05)." (PMID 21731499, 2011). "Additionally, mice with decreased Atp1a2 activity display augmented fear/anxiety behaviors and enhanced neuronal activity." (PMID 36534642, 2022). "This may account for higher male baseline expression of genes such as Atp1a2, Ppp3r1, and Nrn1, and a lack of an Egr1 effect on the expression of these genes and related phenotypes, such as anxiety-related behaviour, due to a possible ceiling effect in males." (PMID 41390827, 2025).
Hypertension (5 papers, 2013 to 2022). The presence of chronic increased pressure in the systemic arterial system. "Although hypertension is one of the most important risk factors for AAA and ATP1A2 is involved in the regulation of blood pressure, whether ATP1A2 participates in the pathological processes of AAA remains unknown." (PMID 35441443, 2022). "Our results also show that both miR-192-5p and miR-204-5p could regulate ATP1A2 expression and it has been previously shown that this α2-isoform of the Na/K-ATPase pump mediates ouabain-induced hypertension in mice and increased vascular contractility in vitro." (PMID 31775784, 2019). "Our study reported that the ATP1A2 specifically expressed in VSMCs was significantly downregulated in AAA, which was confirmed to have the ability to regulate blood pressure in many previous studies, thus implying a potential therapeutic target for patients with hypertension and AAA." (PMID 35441443, 2022). "As NPPA has been demonstrated to inhibit NFAT activation, this DS‐induced up‐regulation of NPPA could explain why RCAN1 was not up‐regulated in DS‐treated rats, even though crucial Ca2+‐handling genes (ATP1A2, SERCA2A and PLN) were dysregulated upon DS‐induced hypertension." (PMID 31368189, 2019).
Intellectual disability (4 papers, 2021 to 2025). "Overall, CACNA1A and ATP1A2 mutations have functional consequences, including impairments in the cognitive ability of patients and, in some cases, intellectual disability following multiple attacks." (PMID 38674378, 2024). "Some patients with HM because of CACNA1A and ATP1A2 mutations have reported developing mental retardation and cognitive disorder following migraine attacks." (PMID 38674378, 2024).
microcephaly (4 papers, 2019 to 2025). A congenital or acquired developmental disorder in which the circumference of the head is smaller than normal for the person's age and sex. "Homozygous truncating mutations in ATP1A2 have been associated with early lethal hydrops fetalis, arthrogryposis, microcephaly, and polymicrogyria, although this seems to be a very rare case." (PMID 39859528, 2025). "Homozygous Atp1a2 knock-out (KO) mice die immediately after birth, and recently biallelic loss of function variants in ATP1A2 have been reported in humans, resulting in death neonatally, with features of hydrops fetalis, microcephaly, arthrogryposis and extensive cortical malformations." (PMID 31226929, 2019).
migraine headache (4 papers, 2013 to 2020). "In addition, several other genes were significantly upregulated, including genes associated with neuronal survival (PDE5A) and certain classes of migraine headaches (ATP1A2)." (PMID 25337697, 2014). "Our data indicate that common variants in the ATP1A2 gene do not play a large role in early-onset ischemic stroke risk or migraine headache." (PMID 23459313, 2013).
Stroke (4 papers, 2013 to 2025). Sudden impairment of blood flow to a part of the brain due to occlusion or rupture of an artery to the brain. "Association analyses between thirteen ATP1A2 SNPs on ITMAT-Broad-CARe array and stroke were initially performed." (PMID 23459313, 2013). "Additional studies will be required to confirm our findings in early-onset stroke and to explore the relationship between ATP1A2 and older-onset stroke." (PMID 23459313, 2013). "As such, these data provide evidence that there may be a common pathway between the protein product of previously identified stroke-related genes and the ATP1A2 gene." (PMID 23459313, 2013).
channelopathy (3 papers, 2025). Channelopathies are a group of diseases caused by the dysfunction of ion channel subunits or their interacting proteins. "Shared genetic mutations, particularly in genes encoding ion channel subunits such as CACNA1A, SCN1A, and ATP1A2, further support a common channelopathy model." (PMID 40949139, 2025). "Among molecularly diagnosed cases SCN1A, SCN2A, KCNQ2, SCN8A, and ATP1A2 were identified as channelopathy-related genes, representing 7 patients." (PMID 40083435, 2025).
Encephalopathy (2 papers, 2023 to 2025). Encephalopathy is a term that means brain disease, damage, or malfunction. "FHM type 2 (FHM2), associated with ATP1A2 mutations, disrupts astrocytic Na+/K+-ATPase function and may present with seizures, encephalopathy, or prolonged neurological deficits." (PMID 41146775, 2025). "Among patients with ATP1A2 mutations, 39.1% presented with encephalopathy." (PMID 37576133, 2023).
epileptic seizures (2 papers, 2021 to 2024). "Seizures are commonly observed in ATP1A2- and ATP1A3-related neurological disorders, and in a mouse model of Alzheimer’s diseases, seizures are exaggerated by low ASC levels." (PMID 33544780, 2021).
episodic ataxia type 2 (2 papers, 2020 to 2025). A form of hereditary episodic ataxia (EA) characterized by paroxysmal episodes of ataxia lasting hours, with interictal nystagmus and mildly progressive ataxia. "Episodic Ataxia Type 2 (EA2) is related to genetic changes in CACNA1A gene among others, such as ATP1A2 gene." (PMID 40111503, 2025).
glial tumors (2 papers, 2022 to 2025). "Expression of ATP1A2 (alpha subunit of Na/K-ATPase specific for glial cells) was higher in both glial tumors versus neuronal-specific ATP1A1 in patients on anti-seizure medications." (PMID 40867621, 2025).
glioblastoma (2 papers, 2021 to 2022). The most malignant astrocytic tumor (WHO grade IV). "However, MGH57 (grade IV glioblastoma) revealed a relatively small subpopulation of malignant cells that do not express OLIG1, OLIG2, DLL1, CCND1, and IGFBPL1, but express ALDOC and ATP1A2." (PMID 33607293, 2021).
mood disorder (2 papers, 2014 to 2016). A cognitive disorder a disturbance in which the person's mood is hypothesized to be the main underlying feature. "Of the identified proteins, only two, 14-3-3ζ and ATP1A2, showed a significant nicotine × mood disorder interaction." (PMID 27559543, 2016). "Only two putative interactors, 14-3-3zeta and ATP1A2 differed significantly with both tobacco use and mood disorders." (PMID 27559543, 2016).
Nystagmus (2 papers, 2017 to 2024). Rhythmic, involuntary oscillations of one or both eyes related to abnormality in fixation, conjugate gaze, or vestibular mechanisms. "Chronic features, such as progressive ataxia and gaze-evoked nystagmus, have been reported to be dependent on the gene involved as they occur in only 60% of FHM type 1 caused by pathogenic variants in CACNA1A (FHM1) but rarely in FHM type 2 caused by ATP1A2 variants (FHM2)." (PMID 38674378, 2024).
Obesity (2 papers, 2019 to 2025). Accumulation of substantial excess body fat. "In line with SERCA2A, transcription of ATPase, Na+/K+ transporting alpha 2 (ATP1A2), was significantly lower in response to obesity and DS treatment." (PMID 31368189, 2019).
periodic paralysis (2 papers, 2018 to 2025). "ATP1A2, which encodes the Na+/K+-ATPase α2 isoform, is highly expressed in both CNS and muscle tissue; mutations can cause hypokalemic periodic paralysis and neuromuscular excitability disorders, underscoring its importance in electrophysiological stability." (PMID 40870030, 2025). "Our data provide important evidence supporting a leak current as the major pathomechanism underlying hypokalaemic periodic paralysis and indicate ATP1A2 as a new hypokalaemic periodic paralysis gene." (PMID 30423015, 2018).
aneurysm (1 paper, 2022). Bulging or ballooning in an area of an artery secondary to arterial wall weakening. "The GEO data and our own verification data both show that the expression level of ATP1A2 is significantly reduced in aneurysms." (PMID 35441443, 2022). "Notably, ATP1A2 was the only common DEGs that was significantly downregulated in both human and mouse AAA samples after intersecting the DEGs of Groups 1–4, which suggested the ATP1A2 as a conservative regulator involved in human and mouse aneurysms." (PMID 35441443, 2022).
atrial septal aneurysm (1 paper, 2018). "We describe the case of one patient with pure sporadic hemiplegic migraine (SHM) with a novel ATP1A2 gene variant and a large patent foramen ovale (PFO) with atrial septal aneurysm." (PMID 29867740, 2018).
behavioural disorders (1 paper, 2012). "Transient or permanent neuropsychiatric features have been rarely associated with ATP1A2 mutations: confusion, behavioural disorders, borderline personality and cognitive retardation." (PMID 22661290, 2012).
bladder cancer (1 paper, 2026). "To determine the impacts of differential ATP1A2 expression on bladder cancer cells, we established an ATP1A2 overexpression cell line from 5637 cells with low ATP1A2 expression." (PMID 41533486, 2026). "Subsequently, JuA was used to treat bladder cancer cells, and changes in ATP1A2 protein levels and mitochondrial energy metabolism were examined." (PMID 41533486, 2026). "This study elucidated the molecular mechanism by which JuA regulates mitochondrial energy metabolism and induces apoptosis in bladder cancer cells through targeted inhibition of ATP1A2." (PMID 41533486, 2026). "This study elucidates the carcinogenic mechanisms of ATP1A2 in bladder cancer and provides an experimental basis for the development of precise ATP1A2-targeted treatment strategies targeting ATP1A2." (PMID 41533486, 2026). "ATP1A2 overexpression enhanced the viability and inhibited the apoptosis of bladder cancer cells and promoted mitochondrial energy metabolism in vitro, whereas ATP1A2 knockdown had the opposite effects." (PMID 41533486, 2026). "As tumor onset and progression are complex processes involving abnormalities in multiple genes and signaling pathways, targeting ATP1A2 alone is possibly insufficient for effective bladder cancer treatment." (PMID 41533486, 2026). "This innovative discovery provides a solid experimental foundation for the development of safe and effective ATP1A2-targeted therapeutic strategies, facilitating the precise and personalized treatment of bladder cancer in the future." (PMID 41533486, 2026). "Here, ATP1A2 knockdown significantly increased the oxidative stress, decreased the ΔΨm, and disrupted the mitochondrial ultrastructure in bladder cancer cells." (PMID 41533486, 2026). "In this study, in vitro experiments confirmed the inhibitory effects of JuA on bladder cancer cells and preliminarily indicated that JuA induces apoptosis by regulating ATP1A2 expression, which affects mitochondrial energy metabolism." (PMID 41533486, 2026). "To confirm that ATP1A2 expression levels affect bladder cancer cells, we established an ATP1A2 knockdown cell line from T24 cells." (PMID 41533486, 2026). "JuA exerts inhibitory effects on bladder cancer cells; its unique action mechanism of influencing mitochondrial energy metabolism by targeting ATP1A2 strongly supports its therapeutic application for cancer." (PMID 41533486, 2026). "Phenotypic assays, such as proliferation and apoptosis assays, were performed to verify the cancer-promoting effects of ATP1A2 in bladder cancer." (PMID 41533486, 2026). "Notably, JuA effectively regulated ATP1A2 expression, thereby influencing mitochondrial energy metabolism and triggering apoptosis in bladder cancer cells." (PMID 41533486, 2026). "We assessed ATP1A2 expression levels using different bladder cancer cell lines." (PMID 41533486, 2026). "ATP1A2 overexpression and knockdown bladder cancer cell models were constructed." (PMID 41533486, 2026). "Notably, this study revealed that ATP1A2 influenced mitochondrial energy metabolism in bladder cancer cells, suggesting a new avenue for controlling the growth and promoting the apoptosis of tumor cells." (PMID 41533486, 2026). "Compared to those in RWPE-1 normal human prostate epithelial cells, ATP1A2 levels were significantly upregulated in the UMUC3, 5637, RT4, and J83 bladder cancer cell lines, with the most obvious upregulation observed in the T24 cells." (PMID 41533486, 2026).
bladder urothelial carcinoma (1 paper, 2020). "ATP1A2 expression was significantly lower in breast invasive carcinoma, bladder urothelial carcinoma and colon adenocarcinoma (all p < 0.001) than in the adjacent normal tissues." (PMID 32684846, 2020).
breast carcinoma (1 paper, 2022). "Previously, ATP1A2 expression was found to be downregulated in breast cancer." (PMID 35498536, 2022).